TAP2 (transporter 2, ATP binding cassette subfamily B member)
Diseases named in the same sentence as TAP2 in open-access papers (continued):
Sharing a sentence is not in itself a finding about the gene and the disease.
allergic disease (2 papers, 2019 to 2026). An immune response that occurs following re-exposure to an innocuous antigen, and that requires the presence of existing antibodies against that antigen. "Moreover, the study pointed out two more genetic variants related to HLA-DQA1 rs9272131, previously indicted to be involved in allergies, together with variants in the TAP2 gene, located in close proximity to the HLA-DQA1 variant, also with previously reported connections with asthma and allergy." (PMID 30832275, 2019).
Autoimmunity (2 papers, 2009 to 2025). The occurrence of an immune reaction against the organism's own cells or tissues. "Some of these regions have previously been associated with autoimmunity; for example rs10484565 falls in a gene called TAP2, which encodes a membrane-associated protein that is a member superfamily of ATP-binding cassette (ABC) transporters." (PMID 20041220, 2009).
colorectal cancer (2 papers, 2022 to 2025). A primary or metastatic malignant neoplasm that affects the colon or rectum. "Multiplexed spectral fluorescence microscopy in colorectal cancer patient tissue microarray confirmed the absence of induced expression of LMP2 and TAP2-positive cells in hypoxic areas stained with the hypoxia marker CAIX." (PMID 39753950, 2025).
Crohn disease (2 papers, 2022 to 2025). A gastrointestinal disorder characterized by chronic inflammation involving all layers of the intestinal wall, noncaseating granulomas affecting the intestinal wall and regional lymph nodes, and transmural fibrosis. "Additionally, the TAP2 gene was identified as a member of whole blood gene panel to distinguish Crohn’s disease and ulcerative colitis." (PMID 36145641, 2022). "It was also shown that the TAP2 locus may play an important role in Crohn’s disease heterogeneity and steroid responsiveness." (PMID 36145641, 2022).
hypothyroidism (2 papers, 2024 to 2025). Abnormally low levels of thyroid hormone. "Significantly, TAP2 was also identified in all three traits within the T2D‐hypothyroidism/myxoedema‐hypoglycaemia relationship." (PMID 39238070, 2024).
medulloblastoma (2 papers, 2009 to 2023). A malignant, invasive embryonal neoplasm arising from the cerebellum. "We investigated expression of four essential components of MHC class I (heavy chain, β2m, TAP1 and TAP2) in 10 medulloblastoma mRNA samples, a tissue microarray containing 139 medulloblastoma tissues and 3 medulloblastoma cell lines." (PMID 19594892, 2009). "The expression of the essential components of the MHC class I antigen-processing machinery: HLA heavy chains (A and B), β2m, TAP1 and TAP2 was first evaluated using RNA from ten frozen medulloblastoma specimens." (PMID 19594892, 2009). "We therefore analyzed HLA heavy chains, β2m, TAP1, TAP2 and CD45 intracellular and/or cell surface expression using medulloblastoma tissue microarrays." (PMID 19594892, 2009). "Therefore, contamination by infiltrating peripheral white blood cells cannot account for positive heavy chain, TAP1, TAP2 and β2m staining in most of these cases and MHC class I expression appears to be genuinely derived from medulloblastoma cells." (PMID 19594892, 2009). "Therefore, we conclude that there is a small subset of medulloblastomas that may express all components required for functional MHC class I molecules, whereas at least one essential component (heavy chain or TAP2) is missing in most tumor samples." (PMID 19594892, 2009).
prostate carcinoma (2 papers, 2014). A carcinoma that arises from epithelial cells of the prostate gland. "We demonstrated DNA demethylation of the promoter sequences of selected antigen-presenting machinery genes (TAP-1/LMP-2, TAP-2) upon IFNγ treatment both in the MHC class I-deficient tumour cell line TC-1/A9 and in the prostate cancer cell line TRAMP-C2." (PMID 25071011, 2014). "Immunohistochemistry analysis of prostate carcinomas 72 h post-irradiation showed increased expression of the immunoproteosome components LMP2 and LMP7, the peptide transporter TAP2, and the chaperones tapasin and calreticulin." (PMID 24480782, 2014).
sarcoidosis (2 papers, 2020 to 2022). Sarcoidosis is a multisystemic disorder of unknown cause characterized by the formation of immune granulomas in involved organs. "A polymorphism of TAP2 detected in patients with sarcoidosis further validated this point." (PMID 36203777, 2022). "TAP2 (transporter 2, ATP binding cassette subfamily B member) moves protein fragments from foreign invaders into the endoplasmic reticulum in close connection with major histocompatibility complex (MHC) class I proteins and TAP2 polymorphisms have been highlighted in European cases of sarcoidosis." (PMID 32823753, 2020). "Non-MHC genes, TAP1, and TAP2, encoding the transporter associated with antigen processing, which participate in the antigen processing pathways prior to its presentation, are also interesting candidates and have been observed to be upregulated in sarcoidosis." (PMID 36203777, 2022).
Sepsis (2 papers, 2022 to 2025). Sepsis is defined as life-threatening organ dysfunction caused by a dysregulated host response to infection. "Results of qRT-PCR validated the higher expression level of B2M as well as lower expression level of HLA-DQA1, HLA-DPA1, TAP1, and TAP2 in sepsis samples compared to control sample." (PMID 35685286, 2022). "Results of qRT-PCR validated the higher expression level of B2M as well as lower expression level of HLA-DQA1, HLA-DPA1, TAP1, and TAP2 in sepsis samples compared to control samples." (PMID 35685286, 2022). "Compared with healthy controls, B2M was significantly upregulated in sepsis samples yet the expression level of HLA-DQA1, HLA-DPA1, TAP1, and TAP2 was significantly lower in sepsis specimens." (PMID 35685286, 2022). "In a study involving 306 patients with sepsis, four subtypes were established, with Mars 1 having the most severity and highest mortality rate; this subtype was associated with specific genes (BPGM and TAP2)." (PMID 40504881, 2025).
Sjögren Syndrome (2 papers, 2019 to 2025). "The upregulation of TAP2 in Sjögren Syndrome has been previously reported, aligning with our finding in this study." (PMID 40149556, 2025). "Additional genetic polymorphisms reported to be associated with risk for Sjögren’s syndrome include variants of interleukin 10 (IL-10), tumor necrosis factor (TNF), antigen peptide transporter 2 (TAP2), and 2′-5′-oligoadenylate synthetase 1 (OAS1)." (PMID 30626116, 2019).
small cell lung carcinoma (2 papers, 2020 to 2021). Small cell lung cancer (SCLC) is a highly aggressive malignant neoplasm, accounting for 10-15% of lung cancer cases, characterized byrapid growth, and early metastasis. "Down-regulated expression of TAP2 and TAP1 may partially deficient HLA Class I expression and then deficient antigen processing in small cell lung cancer lines (SCLC)." (PMID 32867763, 2020).
ulcerative colitis (2 papers, 2022 to 2025). An inflammatory bowel disease involving the mucosal surface of the large intestine and rectum. "On the other hand, TAP2 was also identified as a tissue-related common gene for ulcerative colitis in an integrative study of transcriptome-wide association analysis and mRNA expression profiles." (PMID 36145641, 2022). "Moreover, TAP2 was one of the identified differentially expressed genes between biopsies from ulcerative colitis patients who were naïve with respect to the treatment and healthy biopsy samples." (PMID 36145641, 2022).
atherosclerosis (1 paper, 2024). A disease characterized by the build-up of fatty material and calcium deposition in the arterial wall resulting in partial or complete occlusion of the arterial lumen. "We have identified SLA‐I and TAP2 as potential susceptibility genes of atherosclerosis, highlighting the importance of antigen processing and immune response in atherogenesis." (PMID 38720469, 2024). "TAP2 protein was involved in the development of atherosclerosis, as expected." (PMID 38720469, 2024). "Our finding that the MHC region genes SLA‐I and TAP2 play an important role in immune response highlights the screening role and preventive significance of SLA‐I and TAP2 genotyping in early clinical atherosclerosis." (PMID 38720469, 2024). "Moreover, the STARNET study indicated that CD8+ T cells indirectly communicated with TAP2 through TAPBP and B2M, which suggested that there may be an immune system imbalance in the atherosclerosis process." (PMID 38720469, 2024).
biliary atresia (1 paper, 2020). A rare, biliary tract disease characterized by progressive obliterative cholangiopathy of the intra- and extrahepatic bile ducts, occurring in the embryonic/ perinatal period, leading to severe and persistent neonatal jaundice and acholic stool. "Interestingly, this atlas unveiled that ABCB2/TAP1 may have TAP2‐independent functions in the brain and that biliary atresia (BA) and control livers have quite different ABC transporter profiles." (PMID 33128234, 2020).
bladder cancer (1 paper, 2025). "TAP2 rs241447 variants has been recently reported to affect mRNA expression in bladder cancer tissue." (PMID 40141198, 2025).
bronchiectasis (1 paper, 2025). Segmental, irreversible dilation of the bronchial tree resulting in the accumulation of secretions which leads to obstruction. "We found that chronic necrotizing granulomatous skin lesions and childhood-onset bronchiectasis were common but not universal clinical features of TAP1, TAP2, TAPBP, and B2M deficiency." (PMID 41298860, 2025).
colon adenocarcinoma (1 paper, 2024). "Moreover, among 19 Hub-MHCsig, HLA-DMA, HLA-DMB, and HLA-DOA were positively correlated with microsatellite instability in colon adenocarcinoma, while TAP2, TAP1, and HLA-F were negatively correlated with microsatellite instability in testicular germ cell tumors." (PMID 38714579, 2024).
colorectal adenocarcinoma (1 paper, 2021). The most common type of colorectal carcinoma. "The differential expression analysis of 5561 proteins in 95 colorectal adenocarcinoma (COAD) samples indicated high levels of TAP2 (log Fold Change [FC] = -1.33), PARP14 (logFC = -1.25), and GBP4 (logFC = -1.09) in the RSI-Low tumours." (PMID 34078917, 2021).
colorectal tumours (1 paper, 2021). "Differential proteomic analysis identified significantly higher TAP2 expression in RSI-Low colorectal tumours." (PMID 34078917, 2021).
cyst (1 paper, 2019). A sac-like closed membranous structure that may be empty or contain fluid or amorphous material. "T. gondii interaction with TAP1 and TAP2 could block antigen processing to help hide the cyst during chronic infection or it might assist in nutrient acquisition across the cyst wall." (PMID 31726967, 2019).
demyelination (1 paper, 2023). "Future work should also investigate neuronal expression of antigen-processing genes, such as PSMB8 and TAP2, during acute inflammatory demyelination." (PMID 37676734, 2023).
dengue (1 paper, 2015). "Polymorphisms of the TAP1 and TAP2 genes could be directly associated with the risk of developing dengue disease among the primary-infected individuals." (PMID 26645066, 2015). "Both TAP1 and TAP2 are located within the MHC class II region and homozygosity of the TAP1 at position 1333 and 1637 and for TAP2 at position 2379, respectively, was found to protect against developing severe forms of dengue." (PMID 26645066, 2015).
esophageal cancer (1 paper, 2022). A primary or metastatic malignant neoplasm involving the esophagus. "These coding region SNPs at the TAP1 and TAP2 genes have been associated with rheumatoid arthritis, systemic lupus erythematosus, esophageal cancer, multiple myeloma and chronic lymphocytic leukemia, and tuberculosis." (PMID 36619767, 2022). "However, the TAP2 SNP p.Val379Ile A allele was associated with the risk of esophageal cancer in Chinese patients with HPV+ and with cervical cell aneuploidy in our study population." (PMID 36619767, 2022).
fibrosarcoma (1 paper, 2018). A malignant mesenchymal fibroblastic neoplasm affecting the soft tissue and bone. "In order to avoid confounding immunity to the RMA/S cells themselves, we used CRISPR/Cas9 to generate a B6-syngeic Tap2-/- MCA205 fibrosarcoma cell line." (PMID 30499773, 2018).
Hepatitis (1 paper, 2024). Inflammation of the liver. "Upregulated ISGs (ISG20, IFI16, TAP2, GBP1, PSMB9) in the hepatitis phase were associated with T cell and macrophage infiltration and positively correlated with ALT levels." (PMID 39135698, 2024).
HIV-1 infection (1 paper, 2020). The type species of lentivirus and the etiologic agent of acquired immunodeficiency syndrome (AIDS). "In summary, results of this study showed significant association of the genetic variants of TAP2 (A/G exon 11) (T665A) gene polymorphism with increased risk of HIV-1 infection." (PMID 31732831, 2020). "The heterozygous A/G and the homozygous variant G/G genotypes of SNPs in TAP2 (A/G exon 11) (T665A) gene polymorphism investigated in this study were found to be strongly associated with risk of HIV-1 infection." (PMID 31732831, 2020). "This case–control analysis might suggest a possible role of TAP2 (A/G exon 11) (T665A) gene in the susceptibility to HIV-1 infection and disease outcome among North Indian patients." (PMID 31732831, 2020). "The present result suggested that individuals possessing the variant G allele of TAP2 (A/G exon 11) (T665A) had an elevated risk of HIV-1 infection as the large proportion of HIV-positive individuals carried this variant as compared to HIV-1 seronegative groups." (PMID 31732831, 2020). "Therefore, the results of the present study suggests polymorphism of TAP2 gene, which plays a pivotal role in HLA class I antigen-presenting pathway might be associated with increased risk of HIV-1 infection among seropositive North Indians." (PMID 31732831, 2020). "To determine the correlation between HIV-1 infection and the TAP1 and TAP2 genes polymorphisms, we performed PCR–RFLP assay of these genes in 500 HIV-1 seropositives and the matched seronegative individuals." (PMID 31732831, 2020).
inflammatory bowel disease (1 paper, 2022). A spectrum of small and large bowel inflammatory diseases of unknown etiology. "It was also noted that the expression of TAP2 was elevated in inflammatory bowel disease in comparison with the controls." (PMID 36145641, 2022).
lung adenocarcinoma (1 paper, 2025). A carcinoma that arises from the lung and is characterized by the presence of malignant glandular epithelial cells. "No consistent associations between TAP1 or TAP2 downregulation and age, gender, disease stage or smoking status were identified, and the frequency of cancer cell TAP1 and/or TAP2 downregulation was comparable across lung adenocarcinomas harboring activating mutations in EGFR or KRAS." (PMID 40091029, 2025). "Similar results were obtained in the human lung adenocarcinoma cells PC9 (EGFR mutant) displaying higher baseline TAP2 expression than A549." (PMID 40091029, 2025). "To investigate mechanisms mediating cancer cell TAP2 downregulation in NSCLC, we evaluated the frequency of deleterious TAP2 genetic variants in human lung adenocarcinomas and squamous-cell carcinomas from The Cancer Genome Atlas (TCGA) cohort analyzed using whole exome DNA sequencing." (PMID 40091029, 2025).
lymphopenia (1 paper, 2019). Reduction in the number of lymphocytes. "Isolated CD8 lymphopenia with preserved CD4 counts can be seen with TAP1, TAP2, and ZAP70 defects." (PMID 31572360, 2019).
nasopharyngeal carcinoma (1 paper, 2020). A carcinoma arising from the nasopharyngeal epithelium. "EBV-encoded miRNAs have been reported to downregulate TAP1, TAP2, and ERAP2 mRNA in infected primary B cells, and the TAP2 mRNA was similarly reduced in EBV-associated nasopharyngeal carcinomas." (PMID 32098275, 2020).
Nephroblastoma (1 paper, 2023). An embryonal neoplasm characterized by the presence of epithelial, mesenchymal, and blastema components. "Notably, HLA-B, TAP1 and TAP2 transcript levels were lower than the minimum values of control normal tissues (brain and testis) in ~80% of PDXs (32 out of 44), and B2M levels were also low in neuroblastoma, nephroblastoma, and all but one rhabdomyosarcoma tumors." (PMID 38318504, 2023).
Obesity (1 paper, 2023). Accumulation of substantial excess body fat. "The abundance of different obesity related proteins such as LEP, ITGAL, IKBIP, H2-AA, TAP2 and FABP5 was very low in AdEVs from lean mice and was detected in only one or no biological replicate." (PMID 36759608, 2023).
osteosarcoma (1 paper, 2023). A usually aggressive malignant bone-forming mesenchymal neoplasm, predominantly affecting adolescents and young adults. "Furthermore, 49 (10.6%) tumors had LOH affecting APP gene(s) in the HLA region (TAP1/2, TAPBP, PSMB8/9, HSPA1A-L), including 14 (20.6%) osteosarcoma and five (22.7%) GBM cases with LOH in both TAP1 and TAP2." (PMID 38318504, 2023).
rubella (1 paper, 2025). A viral infection caused by the rubella virus. "Unfortunately, to date, no therapeutic approach was consistently successful against chronic rubella infection, except hematopoietic stem cell transplantation, including in one patient with concomitant TAP1 and TAP2 deficiency." (PMID 41531537, 2025). "With two previous isolated reports, our findings suggest that inherited TAP1 and TAP2 deficiencies specifically predispose to skin RuV infection; they should not be vaccinated with live-attenuated rubella vaccines." (PMID 41531537, 2025).
teratocarcinoma (1 paper, 2010). A germ cell tumor characterized by the presence of an embryonal carcinoma component and a teratoma component. "Unexpectedly, the NT2 teratocarcinoma cell line shows a low expression of TAP-1 and TAP-2, but express tapasin at normal levels." (PMID 20419139, 2010).